C3 (complement C3)
Diseases named in the same sentence as C3 in open-access papers (continued):
Sharing a sentence is not in itself a finding about the gene and the disease.
tumor (continued). "The results were consistent with our expectations: CCL5, LOX, and C3 were significantly upregulated in tumor tissues, whereas PLG exhibited markedly higher expression in normal tissues." (PMID 40396123, 2025). "On the contrary, oncogenic deletion of MBL or C3 in the extra-tumoral compartment, or the knockdown of C3aR in tumor cells, can potentially be protective against the development of the tumor." (PMID 40002901, 2025). "In CRC, tumor cells were found to produce Complement C3 (C3) component thus leading to modulation of the response of macrophages and its anti-tumor immunity, via the C3a-C3aR axis and PI3K signaling pathways." (PMID 39865094, 2025). "Patients with invasive breast carcinoma showed significantly higher C3 cleavage products in human tumours after chemotherapy." (PMID 39765018, 2025). "Higher abundance of complement proteins C3 and C5 is linked to increased CRC risk and poorer prognosis, and have been implicated in treatment resistance and tumor progression." (PMID 41179292, 2025). "Inhibiting C3 or C5 reversed the invasive phenotype and C3 knockdown reduced tumor progression in vivo." (PMID 39964754, 2025). "In the context to GBM, upregulation of several complements—such as C1q, C3, and C5aR1—has been reported in patient serum, tumor tissues and GBM cell lines." (PMID 40843669, 2025). "Tumor cells located in the cerebrospinal fluid produce complement component 3 (C3), which activates the C3a receptors on the epithelial cells of the choroid plexus." (PMID 40076927, 2025). "C3 cleavage fragments were also found to be deposited near tumour blood vessels in a rapid and transient manner 24 h after radiotherapy." (PMID 39765018, 2025). "One of the mechanisms of tumor development due to fungi is proposed to be inflammation, including the activation of the C3 complement cascade." (PMID 40002901, 2025). "Given the significance of C3 tumor cells identified through single-cell analysis, we aimed to capture prognostic signatures based on the C3 marker genes." (PMID 39664386, 2024). "Our deduction is that the C3, identified as a key subpopulation of Myofibroblasts, likely harbors the most potent interactions with tumor cells." (PMID 38562930, 2024). "C3-deficient CT26 or LLC tumors had higher numbers of T cells and those T cells were in more activated state than WT tumors because tumor-derived C3a promoted accumulation and immunosuppressive activity of tumor-associated macrophages." (PMID 38786066, 2024). "Analysis showed that C3 is expressed by several cell types, including macrophages, microglia, astrocytes, endothelial, T cells, and tumor cells." (PMID 39172519, 2024). "This study confirmed the intra-tumoral activation of the CS, thanks to the in loco production of C1q by the macrophages and given the tumor cells’ secretion of C3 and C4." (PMID 38339243, 2024). "Since we have also observed elevated C3 protein expression in tumor tissues, we then investigated the potential association among C3 protein expression, the recruitment of macrophages, and patients’ prognosis." (PMID 38360860, 2024). "The upregulation of C3 in immunomodulatory stromal cells has previously been identified in mouse and human studies, showing that these cells are capable of influencing the tumour immune response." (PMID 38582812, 2024). "A prior investigation revealed that invasive tumor cells release complement C3 into the CSF, which then interacts with the C3aR receptor on choroid plexus cells." (PMID 38256412, 2024). "Current studies suggest that changes in the C3 gene and its expression can affect tumor immune response." (PMID 39055701, 2024). "Tumor cells also secrete the subsequent complement components, leading to C4 and C3 activation fragment deposition (C4b, C4d, C3b, iC3b, C3d)." (PMID 38339243, 2024). "Studies in the 1990s revealed that pro-CTSL secreted by human melanoma cells cleaves exogenous C3, promoting tumor growth and metastasis." (PMID 38894892, 2024).
tumor (continued). "Mounting evidence suggests that complement C3 promotes tumor angiogenesis via C3a-C3aR, which is expressed by monocytes." (PMID 39527585, 2024). "Tumor production and activation of complement C3 and C5 were necessary for tumor growth in mouse tumor challenge models." (PMID 38786066, 2024). "The involvement of C3 MUC6+ tumour cells in the MHC molecule‐mediated pathways, pertaining to peptide antigen presentation, assumes paramount significance." (PMID 38894657, 2024). "Immunohistochemical staining confirmed extreme polarization of podoplanin, DKK3 and C3 expression in relation to tumor proximity." (PMID 37350578, 2023). "A range of genes showed increased expression within stromal populations distal from tumor including the C3 component of complement and SFRP2, a soluble modulator of Wnt signaling." (PMID 37350578, 2023). "More importantly, deletion of C3 in tumor cells that had high C3 expression enhanced the efficacy of anti–PD-L1 treatment." (PMID 36969185, 2023). "The immune cell infiltration of C3 is also more abundant, and the tumor killing ability is also the strongest." (PMID 36739412, 2023). "Unexpectedly, we found that IFN-γ, a cytokine expressed by infiltrating tumoral T cells and which is generally thought to protect against tumor expansion, markedly increased both C3 (precursor of C3a) and C3aR expression levels." (PMID 37296948, 2023). "C3 mRNA expression was upregulated in all tumor cell lines and was more than 4.5 times higher in A431 and SCC13 cells." (PMID 36980718, 2023). "Mannose‐binding lectin binds to glycans of the Malassezia wall and triggers C3 convertase, which can cleave C3 to C3a, and then C3a binds to C3aR on the surface of the tumor cells, promoting proliferation of PC cells in vitro and tumor growth in vivo." (PMID 37937304, 2023). "Previous studies have demonstrated that C3 regulates tumor initiation and progression through the C3a-C3aR-PI3K-AKT signaling pathway." (PMID 37291119, 2023). "Shown as within patient mean normalized count vs region type for DEG identified in A. (D) Representative immunohistochemical staining of podoplanin, DKK3 and C3 proteins in relation to tumor cells (T) in PDAC tissue." (PMID 37350578, 2023). "Scientist found that tumor cells with leptomeningeal metastasis highly expressed C3(complement component 3) and bound to the C3a receptor in choroid plexus (CP) epithelial cells." (PMID 37228619, 2023). "Our study argues for a positive role of the chemoattractant C3a, abundantly produced (through the cleavage of C3) by tumor cells and TAM, as evidenced by our U251MG and THP1 cell model systems." (PMID 37174113, 2023). "Upregulation of C1q, C3/C3a, C5/C5a in HCC is associated with tumor aggressive phenotypes, such as immune suppression, tumorigenesis, metastasis and stemness." (PMID 38090482, 2023). "Next, we aimed to dissect the contribution of inflammatory mediators during tumor development in regulating the expression of the C3 (precursor of C3a) and its receptor C3aR coupled to PI3K signaling." (PMID 37296948, 2023). "C3 secretion has been shown to promote tumor progression and metastases by regulating the function of ECM proteins." (PMID 37833976, 2023). "Four days after receiving the last dose of the tested complex, the tumor volume in the group of mice treated with complex C3 was significantly reduced compared to the group of untreated mice." (PMID 37569878, 2023). "At first, the cleavage product of C3 followed by a series of reactions finally cleaves C5 into C5a which can promote tumor development by recruiting myeloid-derived suppressor cells (MDSCs)." (PMID 36769748, 2023). "Deposition of C1q and C3 was observed in tumor tissues, suggesting a role for complement in the pathogenesis of GBM." (PMID 37033981, 2023). "Previous studies have shown that C3-liposomes improve antigen presentation and the activation of APCs, resulting in enhanced immune activation and reduced tumor growth." (PMID 38140114, 2023).
tumor (continued). "C3 downregulation by siRNA in ovarian cancer cells SKOV3ip1 inhibits tumor cell growth and migration." (PMID 36969185, 2023). "We found that complement C3a, a fragment released from intact complement C3 following complement activation, was enriched in both human and murine MB tumor tissue, and its receptor was highly expressed on tumor-associated astrocytes (TAAs)." (PMID 35725556, 2022). "Mac-1 is capable of binding complement component 3 (C3) with high affinity and participating in the opsonization and removal of pathogens, tumor cells, and immune complexes." (PMID 36359003, 2022). "In CRC, tumor cells were found to produce C3 component thus leading to modulation of the response of macrophages and its anti-tumor immunity, via the C3a-C3aR axis and PI3Kγ signaling pathways." (PMID 35173724, 2022). "Several studies have shown that complement C3 served as an immune modulator to enhance liver cancer progression through downregulation of T cells and dendritic cells (DC) and upregulation of tumor-related MDSCs." (PMID 36294966, 2022). "Similar to human patient samples, both intact C3 and C3a were distributed intensively in tumor tissue, whereas they were barely detected in the normal cerebella control." (PMID 35725556, 2022). "In the renewed model tumor, an uptake at the periphery of PD-L1-positive tumors (approx. 1.6 %IA/g for C3) and a lower uptake for PD-L1-negative tumors (approx. 1.1 %IA/g for C3) were observed." (PMID 35745666, 2022). "We showed that complement inhibition in genetic C3-/- mice and with the use of pharmacologic agents against the C3a and C5a receptors inhibited tumor growth and metastasis." (PMID 36686777, 2022). "By accumulating on the surface of HCC cells and activating complement cascades, AIM eliminated cancer cells by recruiting tumour cell-killing C3." (PMID 36341431, 2022). "The active forms of complement proteins C3 and C5 (C3a and C5a) are potent anaphylatoxins that recruit immune cells, indicating their potential involvement in promoting immune cell infiltration in the tumour microenvironment." (PMID 36341431, 2022). "In this model, the microbiome was found to activate mannose binding lectin (MBL) of LP and promote cancer progression via C3 activation because the genetic deletion of either MBL or C3 in the extra tumoral compartment resulted in reduced tumor growth." (PMID 35860237, 2022). "In the present study, serum immunoglobulins (IgA, IgG, and IgM), CRP, and complements (C3 and C4) levels were determined to evaluate the effects of neurosurgical tumor resection on humoral immunity." (PMID 36169250, 2022). "It is conceivable that C3 expressed in tumor cells can be cleaved inside these cells in non-C3 convertase fashion by cathepsins similar to cathepsin L in CD4+ T cells." (PMID 35860237, 2022). "We observed that both intact C3 and C3a peptide levels were dramatically higher in MB tumor tissue than in adjacent normal tissue, indicating that C3 is activated during MB development." (PMID 35725556, 2022). "In our ceRNA network analysis, FN1 was found to directly interact with C3 and be regulated by miR-127, miR-216b, and miR-429, which have been reported to be downregulated in various tumors and act as tumor suppressors in RCC." (PMID 34688260, 2021). "Overall, these in-situ analyses confirmed C3 expression and activation within the tumor microenvironment of cSCC, suggesting its contribution to cancer development." (PMID 32682912, 2021). "The Pap test fluid and the cervical swab were more similar to each other than to the tumor extract, with the most spectra assigned to immunoglobulin proteins, and also alpha-1-antitrypsin, serotransferrin and complement C3." (PMID 33413078, 2021). "Our results suggest that C3, C5, C3AR1, and C5AR1 are associated with tumor immune evasion via dysfunctional T-cell phenotypes with a lesser contribution of T-cell exclusion." (PMID 34439277, 2021).
tumor (continued). "They demonstrated using a syngeneic TC-1 mouse model, that C3−/−, C4−/− and C5aR−/− mice have significantly reduced tumour growth." (PMID 33802004, 2021). "As the description above, not limited to C3, a series of complement related proteins, such as Serpind1, Cfd, C5, C1qbp, etc., were upregulated in tumor with YB1 treatment." (PMID 34489962, 2021). "Our results demonstrate that the expression levels of C3, C3AR1, and C5AR1 were inversely associated with tumor purity." (PMID 34439277, 2021). "This is not the first time that C3 has been recognized as an important mediator of EMT; a similar role for C3 has been described in tumor microenvironments and renal disease." (PMID 34360950, 2021). "Together these findings suggest that in an inflammatory microenvironment, C3 can promote tumor growth by fueling epithelial hyperplasia, most likely through pathways mediated by iC3b/C3b/C3d on infiltrating myeloid cells." (PMID 32682912, 2021). "Together, these findings suggest that LMSCs promote tumor metastasis via the MSCs (C3)–neutrophil (C3a receptor) axis." (PMID 34707103, 2021). "We explored the relationships between CNAs of the complement component and the tumor immune microenvironment by examining the correlations between CNAs of C3 C5, C3AR1, C5AR1, and dysfunctional T-cell phenotypes in TCGA cancer cohorts." (PMID 34439277, 2021). "We then intersected the key gene members from both WGCNA analyses corresponding to FOLFOX resistance and tumor recurrence which identified the complement component 3 (C3) gene as the only common element." (PMID 34722636, 2021). "Further analysis revealed that C3, C5, C3AR1, and C5AR1 were associated with tumor immune evasion via dysfunctional T-cell phenotypes with a lesser contribution of T-cell exclusion." (PMID 34439277, 2021). "In a syngeneic model of cervical cancer, primary tumours in the flanks showed C3 dependent tumour growth, activation of the classical pathway of complement, and C5a mediated recruitment of CD45+ CD11b+hi Gr1+ MDSC into tumours." (PMID 33494138, 2021). "C3 is a key member of complement system and promotes tumor progression by suppressing immune system as well." (PMID 34712225, 2021). "It showed that the expression of C3 in tumor with YB1 injection is significantly higher than the control group." (PMID 34489962, 2021). "By contrast, the local production of C3 and the release of C5a disrupt the tumor endothelial barrier, facilitating the homing of T cells and their tumor recruitment." (PMID 34359708, 2021). "In particular, tumor cells were shown to produce C1r, C1s, C4, and C3, whereas C1r and C1s were able to take over the tumor-associated macrophages-produced C1q leading to formation of the initiating C1 complex." (PMID 34572075, 2021). "Overall, our differential expression analysis suggests tumor context and stage-dependent heterogeneity in the expression of complement components C3, C5, C3AR1, and C5AR1 in different cancer types." (PMID 34439277, 2021). "Further correlation analysis revealed that C3, C5, C3AR1, and C5AR1 were associated with tumor immune evasion via dysfunctional T-cell phenotypes with a lesser contribution of T-cell exclusion." (PMID 34439277, 2021). "On the other hand, we performed the immunohistochemical analysis to C3, a canonical marker of complement, in the tumor slices." (PMID 34489962, 2021). "In mouse models of breast cancer C3, C5a, C1q and Factor P have been demonstrated to protect against tumour growth." (PMID 33802004, 2021). "CAFs-3 from the primary tumor showed distinct expression of other chemokines and growth factors, such as C3, CCL5, IGF1, CXCL10, CXCL9, and CXCL14, in addition to CCL19 and IGF2." (PMID 34790166, 2021). "In the C3-Tag tumor model, the expression of SV40-large T antigen in the mammary epithelium under the control of the C3 promoter leads to the development of TNBC in mice." (PMID 32766238, 2020).
tumor (continued). "Localized C3 deposition in the tumor microenvironment is a relevant immune signature for predicting prognosis of GC." (PMID 31928530, 2020). "In the tumor microenvironment as well as in draining lymph nodes, pathological activation of the complement pathway and interplay between immune cells and tumor cells can lead to release of sEVs bound with C3 fragment, ensuing immune modulation." (PMID 32765528, 2020). "The C3 expressed notably by immune cells enhances tumor growth by promoting an immunosuppressive environment." (PMID 33113844, 2020). "Complement C3 activation, characterized by localized deposition of C3 and its effectors together with reduced plasma C3 levels, appears to contribute the tumor progression and poor prognosis in human GC." (PMID 31928530, 2020). "The ability of complement C3 to function in conjunction with EMT contributing towards metastasis is shown by the ability of TWIST1 to regulate C3 expression in tumor cells." (PMID 33718121, 2020). "Genetic ablation of other complement proteins such as C3 was also shown to have profound inhibitory effects on primary tumor growth and metastasis correlating to increased numbers of IFNγ+/TNFα+/IL10+ CD4+ and CD8+ T-cells." (PMID 33718121, 2020). "Enhanced C3 deposition and activation in the microenvironment of GC tissues correlated with local inflammation and tumor cell invasion." (PMID 31928530, 2020). "FHR proteins were shown to enhance complement activation and C3 deposition on surfaces, including altered host surfaces such as those of necrotic cells and tumor cells, but also on microbes." (PMID 32765490, 2020). "Complement C3 is a central component in complement activation, activation of C3 results in the generation of C3a, which is a prominent tumor-promoting factor in TME." (PMID 31931851, 2020). "MBL is required for oncogenic progression, whereas deletion of MBL or C3 in the extratumoral compartment-or knockdown of C3aR in tumour cells are both protective against tumor growth." (PMID 32455985, 2020). "A recent study demonstrated that tumor-cell-derived C3 activates the C3a receptor of the choroid plexus epithelium to disrupt the blood-CSF barrier, which promotes leptomeningeal metastasis." (PMID 31931851, 2020). "In contrast, the expression of C3, at the RNA and protein levels, was specific to the S1 population, even in the wider tumor context and in multiple tumor types." (PMID 32433953, 2020). "Our method, combining C3 activation with a tumor marker (serum CEA), obtained a comparable prognostic value for pathological TNM staging which is supported using the IHC C3 score as an immune signature for GC classification." (PMID 31928530, 2020). "In the bioinformatics TCGA cohort, the overall mRNA levels of C3 expressed in tumor tissues were markedly upregulated compared with normal gastric tissues (P = 0.007)." (PMID 31928530, 2020). "In clear-cell renal cell carcinoma, tumor associated macrophages produce high densities of C1q, which together with tumor cell expressed C1r, C1s, C4, and C3 initiates CP activation." (PMID 33193442, 2020). "Deletion of MBL/C3 in the extratumoral compartment or knockdown of C3aR in tumor cells can inhibit tumor growth." (PMID 33520714, 2020). "The C3 upregulation was further validated in paired tumor and adjacent normal tissues (P = 0.002); however, the C5 expression was not significantly different between paired samples (P = 0.546)." (PMID 31928530, 2020). "Third, we performed a ROC curve analysis including IHC C3 score, plasma C3 level at baseline, pathological stage and two tumor markers to determine the prognostic value for tumor-related death." (PMID 31928530, 2020). "Our results reveal the underlying mechanism of C3, CR4, and C5aR1 in regulating the polarization of tumor-associated macrophages (TAMs) in STAD." (PMID 33614473, 2020).